LINC00941 (long intergenic non-protein coding RNA 941 )
Diseases named in the same sentence as LINC00941 in open-access papers (continued):
Sharing a sentence is not in itself a finding about the gene and the disease.
tumor (22 papers, 2019 to 2025). "In CRC, LINC00941 displayed amplified expression in cancer tissues and showed significant associations with clinical characteristics such as tumor invasive depth, metastasis, and stage." (PMID 38370364, 2024). "Specifically, the deficiency of LINC00941 in tumour cells significantly inhibited cell proliferation, while its overexpression had the opposite effect." (PMID 39392103, 2024). "We also found that elevated expression of TM4SF1-AS1, CASC8, UCA1, and LINC00941 was associated with C1, C2, and C6, suggesting a tumor-promoting effect and poor prognosis." (PMID 36871072, 2023). "We identified that LINC00941 acts as a potential diagnostic and prognostic biomarker in GC, and the expression of LINC00941 is associated with tumor depth and distant metastasis based on the analysis of RNA-seq data from TCGA." (PMID 30723491, 2019). "Loss-of-function analysis confirmed that silence of LINC00941 inhibits GC cells proliferation, migration, and invasion in vitro and modulates tumor growth in vivo." (PMID 30723491, 2019). "Loss-of-function analysis revealed that silence of LINC00941 inhibits GC cells proliferation, migration, and invasion in vitro and modulates tumor growth in vivo." (PMID 30723491, 2019). "In this context, the enhancement of autophagy induced by LINC00941 deficiency may result in tumour suppressive effects." (PMID 39392103, 2024). "However, the expression of LINC00941 expression was associated with tumor depth (p = 0.0197, chi-squared test) and distant metastasis (p = 0.0111, chi-squared test)." (PMID 30723491, 2019). "In this study, we identified that long intergenic non-protein coding RNA 941 (LINC00941) is a potential biomarker for diagnosis and prognosis from the cancer genome atlas (TCGA), and we found that the expression of LINC00941 is associated with tumor depth and distant metastasis in GC." (PMID 30723491, 2019). "Furthermore, we explored the associations between expression of LINC00941 and clinicopathological features, and we found that the expression of LINC00941 was associated with tumor depth and distant metastasis." (PMID 30723491, 2019). "In ESCC 35, 39, elevated expression of LINC00941 in tumor tissues suggests its potential role in ESCC progression." (PMID 38370364, 2024). "Previous studies have highlighted the intricate regulatory mechanisms of LINC00941, demonstrating its influence at both transcriptional and post‐transcriptional levels, thereby impacting tumour proliferation, migration and invasion." (PMID 39392103, 2024). "It was also found that, in LUAD patients, the expression of LINC00941 showed a significant increase as the tumour stage progressed, indicating a positive relation with TNM stage, which was also supported by data from TCGA database." (PMID 39392103, 2024). "Particularly, the cancer‐promoting effects of LINC00941 in various tumours provided evidence of the generalizability significance of LINC00941‐targeting therapy." (PMID 39392103, 2024). "These collective findings highlight the pivotal role of LINC00941 in tumor development and underscore its potential as a promising therapeutic target in various gastrointestinal cancers." (PMID 38370364, 2024). "In GC 45, modulation of LINC00941 affected tumor growth, resulting in smaller tumors and reduced weight upon knockdown." (PMID 38370364, 2024). "During our analysis, we examined the associations between LINC00460, LINC00941, RP11-357H14.17, CTC-241F20.4, clinical features, and tumor infiltration levels in the TCGA-HNSC dataset." (PMID 38553620, 2024). "In the case of ESCC 35, 39, in vivo knockdown of LINC00941 significantly attenuated tumor progression, while its overexpression promoted tumor growth and metastasis." (PMID 38370364, 2024). "Conversely, depletion of LINC00941 resulted in reduced tumor size, growth rate, metastases, and improved prognosis." (PMID 38370364, 2024).
tumor (continued). "The results of staining showed that the enrichment of LINC00941 in the tumor tissues was higher than that in the paracarcinoma tissues." (PMID 37215454, 2023). "The results suggested that LINC00941 significantly promoted tumor growth, with the largest tumors recorded in the LINC00941 group." (PMID 35977942, 2022). "To further investigate the role of LINC00941 in PC tumorigeneses and metastasis, we developed an in vivo subcutaneous tumorigenesis model and an in vivo tail vein injection metastatic tumor model, using PANC-1 cells transduced with lentivirus." (PMID 33414429, 2021). "Further, for LINC00941 and its co-expressed mRNA, in terms of tumor grade, the expression level in G3 was significantly higher than that in G1, and all of these genes showed statistical significance." (PMID 34532296, 2021). "The loss-of-function studies demonstrated that linc00941 knockdown suppressed ESCC cell proliferation, invasion and migration, and also suppressed the in vivo tumor growth." (PMID 34254950, 2021). "According to the bar graph, we found that RP11-334A14.8, RP4-738P11.4, TRBV6-6, LINC00668, and LINC00941 expression levels were higher in the relapsed tumor group than in the primary tumor group." (PMID 34532296, 2021). "LINC00941 was highly expressed in PC tissues and cells, and elevated LINC00941 expression positively correlated with tumor size, lymphatic metastasis, and poor prognosis." (PMID 33414429, 2021). "As well, in vivo tumor formation experiments were also confirmed LINC00941 promoted oncogenesis in nude mice, while si-LINC00941 suppressed oncogenesis." (PMID 33869051, 2021). "The in vivo studies deciphered that linc00941 knockdown remarkably attenuated the tumor progression of the KYSE-510 and KYSE-30 cells in the nude mice." (PMID 34254950, 2021). "In the in vivo studies, we only examined the knockdown effects of linc00941 on the in vivo tumor growth, and the actions of linc00941 in the in vivo tumor metastasis and its related signalling pathways should be determined in the future studies." (PMID 34254950, 2021). "The loss-of-function studies demonstrated that linc00941 knockdown impaired ESCC cell proliferation, invasion and migration, and also repressed in vivo tumor growth." (PMID 34254950, 2021). "LINC00941 is highly expressed in GC samples and promotes GC progression by affecting tumor depth and distant metastasis." (PMID 34722522, 2021). "We found that the expression of RP11-334A14.8, RP4-738P11.4, TRBV6-6, LINC00668, and LINC00941 was higher in the relapsed tumor group than in the primary tumor group." (PMID 34532296, 2021). "As such, we selected RP11-334A14.8, RP4-738P11.4, LINC00668, and LINC00941, which showed higher expression in the relapsed tumor group than in the primary tumor group for qRT-PCR validation." (PMID 34532296, 2021). "Previous RNA‐seq analysis on 458 OSCC patient tumour tissues and 72 normal tissues discovered that long non‐coding RNA LINC00941 was highly expressed in tumours than normal tissues." (PMID 32691935, 2020). "Similarly, in CRC 41, 44, LINC00941 knockdown impaired tumor growth, metastasis, and the formation of lung nodules, while its overexpression increased the number of lung metastatic nodules." (PMID 38370364, 2024). "Moreover, LINC00941 expression levels remained higher in tumour groups than that in normal groups as the sample size was expanded to 67 pairs." (PMID 39392103, 2024). "For HCC 47, LINC00941 is highly expressed in tumor spheres and highly invasive HCC cells." (PMID 38370364, 2024). "In other cancers, LINC00941 is often highly expressed in tumor tissues compared to normal tissues." (PMID 36612299, 2023). "In addition, LINC00941 induced LINC00941 expression in isolated tumor tissues, while si-LINC00941 reduced LINC00941 level after injection." (PMID 33869051, 2021). "In this regard, we examined if PMEPA1 overexpression could attenuate the tumor-suppressive effects of linc00941 siRNA on the KEYSE-510 cells." (PMID 34254950, 2021).
tumor (continued). "Tumor formation in nude mice was performed to evaluate LINC00941 function in vivo." (PMID 33869051, 2021). "Besides, we found that LINC00941 was significantly negatively correlated with tumor purity (r=−0.19, p<0.05) whereas BASP1-AS1 was positively associated with tumor purity (r=0.51, p<0.05)." (PMID 34659218, 2021). "Furthermore, silencing of LINC00941 expression resulted in the inhibition of tumor cell proliferation and metastasis, both in vivo and in vitro." (PMID 33414429, 2021). "Moreover, LINC00941 promoted tumorigenesis in vivo, while si-LINC00941 inhibited tumor development of NSCLC." (PMID 33869051, 2021). "In vivo assay further confirmed the role of LINC00941 in promoting OSCC cell tumour formation." (PMID 32691935, 2020). "Our findings demonstrated that LINC00941 could be a potential regulator of tumor metastasis and cancer cell proliferation." (PMID 30723491, 2019). "Interestingly, based on the RT‐qPCR and chest CT data from 67 pairs of clinical samples, we found that the expression of LINC00941 in tumour tissues was increased as the tumour size increased, which was consistent with the results obtained based on the TCGA‐LUAD dataset." (PMID 39392103, 2024). "Moreover, LINC00941 was reported that its overexpression could accelerate tumor progression in NSCLC via miR-877-3p/VEGFA axis." (PMID 35938013, 2022). "Furthermore, functional enrichment analysis of LINC00941 co-expression network demonstrated that LINC00941 might be an essential regulator of tumor metastasis and cancer cell proliferation." (PMID 30723491, 2019). "Furthermore, through the functional enrichment analysis, we found that LINC00941 might be an essential regulator of tumor metastasis and cancer cell proliferation." (PMID 30723491, 2019). "LINC00941, AP001453.2, and AC026368.1 showed higher expression levels in LUAD tissues than in NAT, but the expression of AC236972.3 was significantly lower in tumor tissues than in NAT." (PMID 35938013, 2022). "Moreover, we found that LINC00668 and LINC00941 could affect tumor grade and TNM stages." (PMID 34532296, 2021). "Followed functional experiments indicated that overexpression of LINC00941 accelerated angiogenesis and NSCLC tumor progression via miR-877-3p/VEGFA axis both in vitro and in vivo." (PMID 33869051, 2021). "Silencing LINC00941 expression significantly suppressed OSCC cell growth in vitro and tumour formation in vivo." (PMID 32691935, 2020). "Thus, our findings confirmed that LINC00941 could modulate tumor growth in vivo." (PMID 30723491, 2019). "In addition, by analysing the LINC00941 expression level in the 67 pairs of LUAD samples, we found that the expression of LINC00941 was significantly positive correlated with tumour size." (PMID 39392103, 2024). "Moreover, the expression of LINC00941 was found to vary with tumour sizes in LUAD patients, especially in small tumours (size <2 cm) that cannot be easily detected by low‐dose CT." (PMID 39392103, 2024). "At present, it is not clear whether CAPRIN2 is also regulated by LINC00941 in NPC and whether the LINC00941/CAPRIN2 axis is involved in regulating ferroptosis and metastasis of tumor cells." (PMID 36276162, 2022). "In this study, we carried out the functional rescue assays, and found that miR-877-3p inhibition attenuated the suppressive actions of linc00941 knockdown in the ESCC cell proliferation and metastasis, suggesting that linc00941 siRNA exerts tumor suppressive effects on ESCC at least via miR-877-3p." (PMID 34254950, 2021). "Considering the essential role of tumor-related neovascularization in the process of tumor invasion and metastasis, we cultured HUVECs with supernatant from NSCLC cells with overexpression or inhibition of LINC00941." (PMID 33869051, 2021). "Indeed, LINC00941 expression was highly up‐regulated in OSCC cell lines and OSCC tumour tissues when compared with normal cells and normal tissues, respectively." (PMID 32691935, 2020).
cancer (16 papers, 2019 to 2025). A tumor composed of atypical neoplastic, often pleomorphic cells that invade other tissues. "LINC00941 has been implicated in various hallmarks of cancer across a variety of cancer types and has been shown to be a potential useful prognostic biomarker." (PMID 36869839, 2023). "The study of LINC00941's regulation of normal human epidermal homeostasis and much of its cancer promoting activity, such as its interactions with ANXA2, were carried out with relation to the conserved terminal exon sequence across all LINC00941 isoforms." (PMID 40521240, 2025). "LINC00941, also known as lncRNA‐MUF, functions as a cancer‐associated mesenchymal stem cell upregulated factor." (PMID 39392103, 2024). "In GI cancers, dysregulated expression of LINC00941 has been observed in cancer cells and tissues, and LINC00941 has been found to function as an oncogene and promote tumorigenesis and progression in GI cancers." (PMID 38370364, 2024). "According to CCK8 and colony formation assays, the inhibition of LINC00941 significantly hampered cancer cell proliferation." (PMID 36837389, 2023). "Several studies in other cancers have suggested that LINC00941 promotes the epithelial-to-mesenchymal transition (EMT)." (PMID 36612299, 2023). "Our study is the first one exploring the role of LINC00941 in ccRCC through bioinformatics analysis and in vitro experiments, which enriched the regulatory effect of LINC00941 in cancer." (PMID 36837389, 2023). "Data showed that LINC00941 promoted cancer cells proliferation, while agomiR-877-3p or si-VEGFA reversed the accelerating effects of LINC00941 in NSCLC progression." (PMID 33869051, 2021). "As well, the para-cancer tissues and cancerous tissues of NSCLC patients in our hospital were collected, and qRT-PCR also indicated that LINC00941 was upregulated in cancer tissues of NSCLC patients." (PMID 33869051, 2021). "As PMEPA1 has been shown to regulate EMT in the cancer progression, the action of linc00941/miR-877-3p/PMEPA1 axis in regulating EMT in KYSE-510 cells was further explored." (PMID 34254950, 2021). "ISH assay used to identify the location and expression of LINC00941 in NSCLC tissues, which showed that LINC00941 mainly located in cytoplasm and was significantly increased in cancer tissues." (PMID 33869051, 2021). "We identified that only LINC00941 is a survival-related, cancer-related, and metastasis-related lncRNA." (PMID 30723491, 2019). "This comprehensive analysis identified a batch of core lncRNAs that exhibited strong associations and high regulatory potential across multiple cancers, including NEAT1, MALAT1, GAS5, TP53TG1, and LINC00941, many of which have been previously confirmed to be closely related to cancer progression." (PMID 41373831, 2025). "It was reported that LINC00941 plays a cancer‐promoting role in NSCLC." (PMID 39392103, 2024). "Similarly, in GC 45, 46, LINC00941 was up-regulated in cancer tissues and exhibited a significant correlation with clinicopathological features, including invasion depth, lymphatic metastasis, and TNM stage." (PMID 38370364, 2024). "Although these cancer types were not previously associated with LINC00941 in the literature, they do coincide with LINC00941’s association with cancer progression in general." (PMID 36869839, 2023). "LINC00941’s predicted and potential role in immune regulation could be a potential new direction for better elucidating its pro-metastatic role in various cancers." (PMID 36869839, 2023). "Upregulation of LINC00941 has been detected in several types of cancers." (PMID 36717549, 2023). "Linc00941 expression has been detected in several types of cancers." (PMID 34254950, 2021). "These seemingly contradictory results suggest that the specific role of LINC00941 in cancer may depend on different contexts." (PMID 32691935, 2020). "In addition, the inhibition of LINC00941 could significantly decrease the invasion and migration ability of cancer cells." (PMID 36837389, 2023).
cancer (continued). "In addition to cancer, there is evidence in the literature that LINC00941 may be involved in cell differentiation." (PMID 36869839, 2023). "However, how the expression of LINC00941 is modulated in cancer tissues has been unknown." (PMID 36612299, 2023). "Considering the essential role of angiogenesis in cancer development, we cultured human umbilical vein endothelial cells (HUVECs) with supernatant of A549 and NCI-1299 cells with LINC00941 or si-LINC00941." (PMID 33869051, 2021). "As EMT is a critical process in cancer cell migration and distal metastasis and PMEPA1 is an important regulator for EMT, we further examined if linc00941/miR-877-3p/PMEPA1 axis regulates EMT in ESCC cells." (PMID 34254950, 2021). "Though the role of linc00941 has been reported in other cancers, we reported the role of linc00941 in ESCC and also demonstrated the importance of the novel linc00941/miR-877-3p/PMEPA1 axis in ESCC progression." (PMID 34254950, 2021). "Among these DEirlncRNAs included in the model, some have been revealed to be related to the development of cancers, such as LINC00958, FOXF1 adjacent non-coding developmental regulatory RNA (FENDRR), LINC01116, and LINC00941." (PMID 34408216, 2021).
digestive system tumors (2 papers, 2022 to 2024). "Additionally, LINC00941 has demonstrated clinical significance in terms of clinical pathology, prognosis, and diagnosis in GI tumors, further reinforcing its potential as a novel therapeutic target." (PMID 38370364, 2024). "Similarly, LINC00941 has also been shown to be closely related to digestive system tumors in multiple studies." (PMID 35754800, 2022).
LINC00941 also shares sentences with these, for which no sentence is quoted: colorectal cancer (4 papers); idiopathic pulmonary fibrosis (2); thyroid cancer (2); chronic hepatitis B (1); Cirrhosis (1); cutaneous squamous cell carcinoma (1); glioblastoma multiforme (1); liver cancer (1); pancreatic adenocarcinoma (1).